CPS1 (carbamoyl-phosphate synthase 1)
Diseases named in the same sentence as CPS1 in open-access papers (continued):
Sharing a sentence is not in itself a finding about the gene and the disease.
cancer (continued). "In cancer cells, the UC is reconfigured/reorchestrated to support high anabolic demand, often involving the dysregulation of key enzymes such as ASS1, ASL, OTC and CPS1." (PMID 42074106, 2026). "Herein, we demonstrate that CPS1 acts as a switch between HCC proliferation and metastasis by increasing intracellular Asp content, reflecting the dynamic needs for amino acids during cancer progression." (PMID 39387452, 2024). "In contrast to CPS1, OTC is downregulated in cancer cells leading to accumulation of ammonia." (PMID 37274280, 2023). "Additionally, the reduction of another enzyme in cancers, argininosuccinate synthase (ASS1), as well as CPS1, elevates cytosolic aspartate levels, thus providing substrates to CAD by facilitating pyrimidine synthesis." (PMID 34638594, 2021). "Our results showed that knockdown of CPS1 does not significantly inhibit cancer cell proliferation, but can make cancer cells more sensitive to ammonia toxicity." (PMID 33869206, 2021). "CCLE analysis showed that CPS1 mRNA was expressed in some cancer cell lines, but most cancer cells did not express OTC and ARG1, implying the urea cycle was down-regulated in cancer cells." (PMID 33869206, 2021). "Both downregulated CPS1 activity (CRhi NSCLC and intrahepatic cholangiocarcinoma tumors) or OTC activity (CRhi HCC tumors) result in severe arginine auxotrophy and therefore reflect a common repression of mitochondrial urea cycle metabolism in these different cancer subtypes." (PMID 35838048, 2022). "Moreover, knockdown of CPS1 did not affect cell colony formation under normal condition, but suppressed the ability of clone formation of cancer cells under 10 mM of NH4Cl." (PMID 33869206, 2021). "ASGPR+CPS1+ CTCs were detected in 29/32 (91%) of HCC patients, and no CTCs were found in healthy volunteers, benign liver diseases and other cancers groups." (PMID 36091119, 2022).
infection (11 papers, 2014 to 2025). The state of being infected such as from the introduction of a foreign agent such as serum, vaccine, antigenic substance or organism. "We next aimed to address how regulatory networks of known brain-infection factors, such as Ure1, Cps1, Itr1a, Itr3c, Mpr1, Plb1, Fnx1, and Rub1, are connected to brain-infection-related kinases and TFs identified in this study." (PMID 32251295, 2020). "We expected that GalNAc would inhibit CPS1 infection because CPS of wild type competitively inhibited CPS1 infection." (PMID 31683584, 2019). "Based on the idea that CPS are the key components of the CPS1 receptor, we tested the effect of monosaccharides comprising CPS on CPS1 infection." (PMID 31683584, 2019). "While GalNAc, GlcNAc, Glc, Gal, and rhamnose did not exhibit any effect on E.O.P., glucosamine and galactosamine inhibited CPS1 infection." (PMID 31683584, 2019). "Maturation of cNK cells after both RH and ME49 infections was also reduced, and immature stages of cNK cells were more pronounced than after cps1-1 infection." (PMID 27721814, 2016). "We observed decrease in splenic cNK cell frequency and numbers 5 days after both type I RH and type II ME49 in comparison to the cps1-1 infection." (PMID 27721814, 2016). "During infection, CPS1 activity decreased by 40% (P=0.001) in WT and 28% (P=0.018) in spf-ash, whereas OTC activity decreased by 7% (P=0.005) in WT and 21% (P=0.015) in spf-ash." (PMID 24271778, 2014). "Intraperitoneal inoculation of cps1-1 triggers robust Th1-based protective immunity to challenge with RH strain tachyzoites and vaccination with this uracil auxotroph also protects mice against infection with lower virulence cyst-forming Toxoplasma strains." (PMID 39440975, 2024). "In contrast, after cps1-1 infection, only mature CD11b+ cNK cells expressed KLRG1." (PMID 27721814, 2016). "Though differences in age of diseased piglets in association with infection by different S. suis cps are overall not well documented, previous studies suggested already that cps1 primarily causes disease in suckling and not in weaning or growing piglets, as the case in cps2 and cps9." (PMID 40682174, 2025). "The expression levels of CPS1, CYP2D6 and CYP3A4 proteins were significantly lower in the 43d M(+) cell group compared to the 1d M(+) cell group, suggesting that the extent of CPS1, CYP2D6, and CYP3A4 inhibition was related to the length of infection." (PMID 29075618, 2017). "Despite this possibility, there was no increase in cNK cell numbers in peritoneum after i.p. infection with replicating parasites, in contrast to non-replicating cps1-1 strain." (PMID 27721814, 2016). "Absolute cNK cell numbers per PEC only increased after cps1-1 infection and not after RH and ME49 infections." (PMID 27721814, 2016). "The transcripts corresponding to two A. rabiei genes previously identified in response to oxidative stress (Ar125, Ar126) and the polyketide synthase pks2 were also found to be over-expressed during infection, but not pks1 and cps1." (PMID 26648917, 2015). "However, CPS extracted from C. perfringens FD1, which is not a CPS1 host, were unable to interfere with CPS1 infection." (PMID 31683584, 2019). "However, infection of CPS1 was inhibited by glucosamine and galactosamine rather than GalNAc." (PMID 31683584, 2019).
metabolic disorders (6 papers, 2016 to 2025). "Carbamoyl phosphate synthetase 1 (CPS1) deficiency is a rare metabolic disorder that, in neonatal onset, is typically characterized by severe life-threatening and neurologically injuring hyperammonemic episodes with high unmet patient need." (PMID 40421838, 2025). "Among the significant findings, two gene–amino acid associations are novel (3-methoxytyrosine and DDC, and acisoga and VNN1) and there are two loci, DDC and CPS1, in which mutations are known to cause autosomal recessive metabolic disorders." (PMID 27884205, 2016). "This study was designed to elucidate the involvement of CPS1 in metabolic disorders, with a particular focus on its role in hepatic gluconeogenesis." (PMID 39193349, 2024). "On the basis of this study, PXA could be considered an interesting probe for further investigations on the development of a new class of CPS1 positive modulators playing a pharmacological role in the therapy of several human diseases and metabolic disorders." (PMID 32498414, 2020).
genetic disorder (3 papers, 2019 to 2023). "Based upon the population frequency of the genetic disorder CPS1 deficiency, there are likely many heterozygous individuals with decreased CPS1 activity (see Discussion)." (PMID 31366360, 2019). "NAGS, CPS1, and citrin sequence variants present in individuals without rare genetic disorders were collected from the gnomAD database." (PMID 37047726, 2023).
kidney disease (3 papers, 2015 to 2024). "Our results confirm previously identified associations of NEMG (NAT8, GATM, SLC22A2, WDR72, NOS3, AGXT2 and CPS1) with kidney disease and kidney function, providing new information that expands these associations to other kidney disease biomarkers." (PMID 38858654, 2024). "The CPS1 locus has been previously found associated with kidney disease, homocysteine, and several metabolite levels including glycine." (PMID 25569235, 2015). "Stable-effect variants mapped to Mendelian kidney disease genes (SLC34A1), but also to creatinine metabolism (CPS1, SLC22A229,30) in line with differential expression in muscle." (PMID 39567532, 2024).
cardiovascular diseases (1 paper, 2020). "Moreover, some of the genes (CPS1, MTHFR, and FADS1,2) that show associations with metabolites and are involved in neuropsychiatric diseases, and/or inborn errors of metabolism are also involved in cardiovascular diseases." (PMID 33177615, 2020).
lung (1 paper, 2020). "CPS1 (carbamoyl‐phosphate synthase 1) is a multi‐domain mitochondrial enzyme that is involved in arginine and pyrimidine metabolism and was shown to be statistically significantly associated with poor overall survival in stage I lung ADC." (PMID 32536039, 2020).
CPS1 also shares sentences with these, for which no sentence is quoted: Encephalopathy (3 papers); argininosuccinate lyase deficiency (2); cholangiocarcinoma (2); colorectal tumors (2); glucose metabolism disorder (2); non-alcoholic steatohepatitis (2); organic acidemias (2); ornithine carbamoyltransferase deficiency (2); small intestinal adenocarcinoma (2); (CPS1) deficiency (1); adenocarcinoma (1); alcohol abuse (1); amino acid metabolic diseases (1); aminoacylase 1 deficiency (1); anaplastic astrocytoma (1); aspartylglucosaminuria (1); atransferrinemia (1); citrin deficiency (1); Cobalamin deficiency (1); developmental delay (1); dimethylglycine dehydrogenase deficiency (1); duodenal cancer (1); epidermolysis bullosa (1); GALE deficiency (1); glycine encephalopathy 1 (1); head and neck squamous cell carcinoma (1); Headache (1); heart disease (1); Hepatitis (1); Huntington disease (1).
A further 37 diseases each share a sentence with CPS1 in 1 paper.